HAS2 (hyaluronan synthase 2)
Diseases named in the same sentence as HAS2 in open-access papers (continued):
Sharing a sentence is not in itself a finding about the gene and the disease.
melanoma (9 papers, 2013 to 2025). A malignant, usually aggressive tumor composed of atypical, neoplastic melanocytes. "Coordinate expression of Id1 or Id3 or CD44 with HAS2 or HAS3 or CD44 was found to be associated with reduced survival of human melanoma patients." (PMID 30297743, 2018). "Decreased coverage of HAS2 immunostaining in melanoma cells was associated with several histopathological factors, including reduced number of tumor infiltrating lymphocytes (TILs) (p = 0.036) and increased horizontal tumor diameter (p = 0.002)." (PMID 27184066, 2016). "Reduced HAS2 immunostaining (coverage and intensity) was associated with melanoma-related death (p = 0.001 and p = 0.016, respectively)." (PMID 27184066, 2016). "Decreased immunostaining of HAS2 in melanoma cells was significantly associated with several known unfavourable histopathologic prognostic markers like increased mitotic count, absence of tumor infiltrating lymphocytes and the nodular subtype." (PMID 27184066, 2016). "Decreased intensity of HAS1 in melanoma cells was related to increased regional metastasis (p = 0.023), while decreased intensity of HAS2 was associated with distant metastasis (p = 0.004)." (PMID 27184066, 2016). "On the other hand, increased intensity of HAS2 in melanoma cells was associated with superficial type (p = 0.047; data not shown)." (PMID 27184066, 2016). "This study indicates that reduced expression of HAS1 and HAS2 is associated with melanoma progression and suggests that HAS1 and HAS2 have a prognostic significance in cutaneous melanoma." (PMID 27184066, 2016). "The loss of HAS2 has shown to be associated with the poor prognosis and recurrence of melanoma." (PMID 35127523, 2021). "In addition, weak immunostaining of HAS2 in melanoma cells is associated with unfavorable histopathologic prognostic markers such as increased mitotic count, absence of tumor infiltrating lymphocytes and nodular subtype." (PMID 27184066, 2016). "Furthermore, decreased HAS1 coverage in melanoma cells (p = 0.007), and decreased intensity of HAS2 in the stromal cells, was positively associated with melanoma-related death (p = 0.038; data not shown)." (PMID 27184066, 2016). "Furthermore, reduced HAS1 and HAS2 immunostaining in the melanoma cells was associated with increased recurrence of melanoma (p = 0.041 and p = 0.006, respectively) and shortened disease- specific survival (p = 0.013 and p = 0.001, respectively)." (PMID 27184066, 2016). "Decreased HAS2 intensity in melanoma cells was also associated with advanced stage (p = 0.047)." (PMID 27184066, 2016). "Upon PACAP action, a strong immune signal was shown in melanoma cells and HAS2 signals were more pronounced than HAS3 signals." (PMID 41465475, 2025). "The reduction of hyaluronan in the tumor tissue has been shown to be due to the loss of HAS1 and HAS2, and increased HYAL2, and this associated with poor prognosis and shortened disease-specific survival in melanoma." (PMID 35127523, 2021). "Our results (2012) as well as others have shown that melanoma cell-secreted factors (PDGF) induce stromal fibroblasts to produce hyaluronan by upregulating HAS2 via PDGFR-PI3K-AKT and p38 MAPK signaling." (PMID 35127523, 2021). "The expression of HAS1 and HAS2 was decreased in deep melanomas and metastases compared to superficial melanomas." (PMID 27184066, 2016). "The immunostaining of both HAS1 and HAS2 was decreased in deeply invasive melanomas and lymph node metastases compared to superficial melanomas and this associated with several known negative prognostic factors." (PMID 27184066, 2016). "Here we demonstrate for the first time that decreased expression of HAS1 and HAS2 favours melanoma progression and metastasis." (PMID 27184066, 2016). "Our results about correlation between decreased immunostaining of HAS1 and HAS2 and decreased survival of patients support the previous works and bring us new information about histopathological changes that happen during melanoma progression." (PMID 27184066, 2016).
melanoma (continued). "Similar to melanoma cells, the strongest HAS1 and HAS2 immunostaining intensity in stromal cells was observed in superficial melanomas." (PMID 27184066, 2016). "Significant adverse prognostic factors for decreased DSS were increased Breslow’s depth (p = 0.001) and decreased HAS1 and HAS2 staining intensity in melanoma cells (p = 0.019 and p = 0.011, respectively)." (PMID 27184066, 2016). "For RFS, significant adverse prognostic factors were deep invasion (p < 0.001) and decreased HAS2 staining intensity of melanoma cells (p = 0.014)." (PMID 27184066, 2016). "Our results demonstrate that the proportion of HAS1 and HAS2 and hyaluronan positive melanoma cells is significantly decreased in lymph node metastases, compared with superficially invasive melanoma." (PMID 27184066, 2016). "Our novel data provides novel information about hyaluronan metabolism in cutaneous melanoma and points towards a significant role for HAS1 and HAS2 in melanoma dissemination." (PMID 27184066, 2016). "In superficial and deep melanomas, the proportion of HAS2 positive melanocytic cells was significantly lower (mean 51-75% and 26-50%, respectively) than in in situ melanomas (p=0.043 and p=0.007, respectively)." (PMID 23560496, 2013). "The proportion of the melanocytic cells stained positively for HAS2 was significantly higher in dysplastic nevi (mean 76-100%, p=0.000) and in situ melanomas (mean 76-100%, p=0.000) compared to benign nevi (mean 26-50%)." (PMID 23560496, 2013). "Then in in situ melanomas, the proportion of HAS2 positive melanocytic cells is higher than in benign nevi, and at this state the hyaluronan content is also increased in melanocytic cells." (PMID 23560496, 2013). "Additionally, a correlation analysis revealed significant positive correlations between HAS2 and chemokine signaling pathways (r = 0.505, p = 0.039) and melanoma (r = 0.510, p = 0.037)." (PMID 39118664, 2024). "The tumor-promoting properties of these transcriptional regulators, and the ability of the HA/CD44 axis to promote their expression in response to BMP stimulation, likely underlies the association between coordinate expression of Id1/Id3 and HAS2/HAS3/CD44, and reduced survival of melanoma patients." (PMID 30297743, 2018). "Similarly, the proportion of HAS2 immunopositive melanoma cells was significantly lower in deeply invasive (pT4) melanomas and LN metastases (pN1) (p = 0.013 and p = 0.012, respectively) compared to superficial melanomas." (PMID 27184066, 2016). "Furthermore, multivariate analysis indicates that decreased expression of HAS1 and HAS2 in melanoma cells are independent prognostic factors." (PMID 27184066, 2016). "In addition, staining intensity of HAS1 in melanoma cells was decreased in LN metastases compared to deeply invasive melanomas (p = 0.018) and HAS2 intensity in melanoma cells was decreased in deeply invasive melanomas compared to superficial ones (p = 0.002)." (PMID 27184066, 2016). "Decreased tumoral hyaluronan content is accompanied by an increase in the hyaluronan degrading enzyme, hyaluronidase 2 (HYAL2), and a decrease in HAS1 and HAS2 expression in invasive melanomas and lymph node metastases compared to benign nevi and in situ melanomas." (PMID 27184066, 2016). "Similarly, decreased HAS2 coverage in melanoma cells was associated with poorer DSS (p = 0.001) and RFS (p = 0.006), and decreased intensity of HAS2 staining was related to shortened DSS (p = 0.014)." (PMID 27184066, 2016). "Furthermore, melanoma cell-derived factors are able to induce hyaluronan synthesis in cutaneous fibroblasts via upregulation of HAS2." (PMID 27184066, 2016). "Similarly, increased distant recurrence was related to reduced HAS1 and HAS2 positive melanoma cells (p = 0.012 and p = 0.001, respectively)." (PMID 27184066, 2016).
melanoma (continued). "Our results indicate that reduced immunopositivity of HAS2 is associated with several known unfavorable histopathologic prognostic markers like a reduced number of tumor infiltrating lymphocytes (TIL), an increased melanoma horizontal diameter, an increased mitotic activity and the nodular subtype." (PMID 27184066, 2016). "The protein expression of HAS2 and HAS3 was minimal in either control melanoma cells or melanocytes, but it dramatically increased in the presence of PACAP in all cases." (PMID 41465475, 2025). "Decreased immunostaining intensity was observed in LN metastases compared with superficial melanomas (p = 0.013 for HAS1, p < 0.001 for HAS2)." (PMID 27184066, 2016). "We have previously demonstrated that decreased expression of HAS1 and HAS2 and increased expression of hyaluronan degrading enzyme HYAL2 correlates with decreased tumoral hyaluronan content in the invasive melanomas." (PMID 27184066, 2016). "Decreased coverage of HAS2 positive melanoma cells was a significant negative prognostic factor (p = 0.039) for DSS, similar to increased stage (p = 0.001) and age (p = 0.035)." (PMID 27184066, 2016). "Likewise, forced expression of HAS2 and HAS3 genes results in HA overproduction, which enhances the tumor forming ability of fibrosarcomas and melanoma cells while abrogation of HAS2 blocks xenograft prostate tumor growth." (PMID 25999946, 2015). "The staining intensity for HAS2 in the stroma was generally low, varying from negative to moderate in benign and dysplastic nevi and in situ melanomas, and from weak to negative in superficial (p=0.001) and deep melanomas (p=0.002) compared to benign nevi." (PMID 23560496, 2013). "Therefore, changes in the relative expression or activation of HAS2 versus HAS3 could critically influence HA size distribution and in turn, modulate melanoma cell behaviour, including adhesion, motility, and interactions with the tumour microenvironment." (PMID 41465475, 2025). "In addition to HAS1 and HAS2 expression, the observed HYAL2 expression may contribute to melanoma progression." (PMID 27184066, 2016).
COVID-19 (8 papers, 2020 to 2025). A disease caused by infection with severe acute respiratory syndrome coronavirus 2. "The hyperactivation of epithelial cells and macrophages manifests in the form of an increased expression of hyaluronan synthase 2 (HAS2), which causes the hypersecretion of HA in severe COVID-19 cases." (PMID 40723879, 2025). "Accumulation of hyaluronan induced by HIS-mediated HAS2 upregulation is a substantial basis for clinical manifestations of COVID-19, especially in lymphocytopenia and pulmonary ground-glass opacity." (PMID 35593963, 2022). "Inflammatory cytokines and inflammatory storm in COVID-19 patients can strongly induce the expression of HA-synthase-2 (HAS2), while hyaluronidase level decreases, resulting in the accumulation of HA and inducing ARDS and pulmonary edema (Shi." (PMID 34163357, 2021). "The recent research revealed that Human Identical Sequences of SARS-CoV-2 (HIS-SARS2) can promote COVID-19 progression by inducing hyaluronan accumulation through activating HAS2 expression, which offers a novel insight into understanding the pathogenic mechanism of SARS-CoV-2." (PMID 35593963, 2022). "Importantly, TNF-α in the lungs of COVID-19 patients induces HA-synthase-2 (HAS2) in EpCAM+ lung alveolar epithelium and CD31+ lung alveolar endothelium and fibroblasts." (PMID 32961074, 2020). "Especially, HIS-SARS2 could upregulate HAS2 in human fetal lung fibroblast cells and promote the synthesis of hyaluronan, a crucial mediator for inflammation, which may be connected to the pulmonary fibrosis of COVID-19." (PMID 35593963, 2022). "Moreover, the major enzyme for hyaluronan synthesis, HAS2, was activated by HIS-SARS2, which promoted hyaluronan accumulation in severe COVID-19 patients." (PMID 35593963, 2022). "In COVID-19 the homeostatic equilibrium between TREG cells (IL-10) and Th17 cells (IL-17) is broken: inflammatory cytokine levels (IL-1, TNF) are elevated in the lungs of COVID-19 patients, resulting in an increase in HA-synthase-2 (HAS2) in alveolar epithelial cells CD31+, EpCAM+ and fibroblasts." (PMID 33160363, 2020).
osteosarcoma (8 papers, 2011 to 2023). A usually aggressive malignant bone-forming mesenchymal neoplasm, predominantly affecting adolescents and young adults. "Its overexpression in osteosarcoma cells reduces HAS2 transcript, while in oral squamous cell carcinoma, it induces HAS2 transcription and hypoxia-induced invasiveness." (PMID 37568628, 2023). "HA synthesized by HAS2 has been reported to play crucial roles in cell proliferation, migration, and invasiveness in osteosarcoma cell lines." (PMID 34233709, 2021). "In relation to osteosarcoma, HAS2-mediated HA synthesis has been reported to play an important role in cell proliferation, migration, and invasiveness in the osteosarcoma cell line MG63." (PMID 34233709, 2021). "In osteosarcoma cells, transcription of HAS2 mRNA synthesis and subsequent HA production are downregulated by HAS2-AS1." (PMID 26550568, 2015).
ovarian carcinoma (8 papers, 2009 to 2023). A malignant neoplasm originating from the surface ovarian epithelium. "Considering the strong association between ovarian cancer aggressiveness and HA deposition, we knocked down HAS2 to evaluate if its expression correlates with ovarian cancer cell lines' aggressiveness." (PMID 35767191, 2022). "Of particular relevance, our experiments highlighted that the expression of HAS1 and especially the expression of HAS2 correlates with poorer survival of ovarian cancer patients." (PMID 35767191, 2022). "In conclusion, HAS2 appeared to be the enzyme of the HA system with the biggest impact on the survival of ovarian cancer patients." (PMID 35767191, 2022). "All in all HAS2 expression goes along with lower OS and PFS of ovarian cancer patients, and, indeed, our experiments suggest that HAS2 seems to be important for stimulating tumour and cell growth and stability and it encourages cell viability." (PMID 35767191, 2022). "CBP treatment increased the secretion of HA in ovarian cancer cell lines by increasing HA synthesis, as we found corresponding increased Has2 and Has3 expression in OVCAR-5 and increased Has3 expression in OV-90 and OVCAR-3 cells." (PMID 24124770, 2013). "Immunohistochemical stainings confirmed that the levels of HAS1 and HAS3 were relatively low in ovarian cancers, while the signal for HAS2 was more widespread, in line with the real-time RT-PCR-analysis." (PMID 19435493, 2009). "We found that HAS1 and HAS2 expression correlated with worse survival of ovarian cancer patients." (PMID 35767191, 2022). "The MTT Assay was used as a well-established and robust assay to assess whether the ovarian cancer cell viability is influenced by HAS2 knockdown." (PMID 35767191, 2022). "At the molecular level, we evaluated basal expression levels of the HA axis in a panel of ovarian cancer cell lines and compared control ovarian cancer cells and HAS2 knockdown cells regarding gene expression of HAS1-3 and HYAL2-3, CD44, RHAMM and versican by qPCR." (PMID 35767191, 2022). "Moreover, the functional impact of the major hyaluronan synthase HAS2 in ovarian cancer cells is so far unclear." (PMID 35767191, 2022). "Therefore, we decided to study the functional impact of HAS2 depletion using an in vitro siRNA approach in human ovarian cancer cell lines." (PMID 35767191, 2022). "It is likely that the tumour inhibitory effects of 4-MU in vivo may be mediated by inhibiting HA in the tumour microenvironment as HRA ovarian cancer cells expressed low levels of HAS2 and HAS3." (PMID 31443261, 2019). "In ovarian cancer patients, high HAS1 levels in ovarian cancer cells but not HAS2 or HAS3 are associated with reduced overall survival." (PMID 21541039, 2011). "Finally, we evaluated if HAS2 depletion may affect the migratory capacity of ovarian cancer cells, employing a scratch wound assay." (PMID 35767191, 2022). "In summary, HAS2 may be an important prognostic factor in ovarian cancer." (PMID 35767191, 2022). "However, as HRA ovarian cancer cells were found to express very low levels of HAS2 and CD44, the in vitro effects of 4-MU in these cells may be via a mechanism other than HA-CD44 signaling." (PMID 31443261, 2019). "DAB2 expression had a significant positive correlation with HA synthesis protein HAS2, HA receptor CD44 and co-receptor toll like receptor 4 (TLR4) in both ovarian cancer cell lines (CCLE) and patient tissues (TCGA: microarray and RNAsequencing data)." (PMID 37815603, 2023). "This is therapeutically significant, as increased HAS2 and HAS3 expression was observed in chemotherapy-resistant ovarian cancer cells." (PMID 35767191, 2022). "HAS1, HYAL1 and HYAL4 mRNA expression is significantly upregulated, whereas HAS2, HYAL2 and HYAL3 mRNA expression is significantly downregulated in ovarian cancer tissue compared to controls." (PMID 35767191, 2022).
ovarian carcinoma (continued). "Our results on the ability of SKOV3 ovarian cancer cell lines to form spheroids confirmed that, effectively, HAS2 could be involved in the reduction of tumour aggressiveness, as we observed a significantly poorer cell cohesion in HAS2 knockdown cells with respect to control cells." (PMID 35767191, 2022). "Our results report that the higher the HAS2 expression, the lower the OS and PFS for ovarian cancer patients." (PMID 35767191, 2022). "Following an evaluation of hyaluronan-related gene expression in the ATCC ovarian cancer panel, we studied SKOV3 and SW 626 ovarian cancer cells subjected to HAS2 siRNA or control siRNA treatment in terms of HAS1-3, HYAL2 and HYAL3 mRNA expression." (PMID 35767191, 2022). "Lower HAS2 expression and high expression of HYAL2 and HYAL3 favours the survival of ovarian cancer patients." (PMID 35767191, 2022). "The expression of the HA synthases HAS2 and HAS3 was significantly increased in chemoresistant compared to chemosensitive primary ovarian cancer cells isolated from patient ascites." (PMID 31443261, 2019). "In this study we found that the expression of the HA synthases HAS2 and HAS3 was significantly increased in chemoresistant compared to chemosensitive primary ovarian cancer cells isolated from patient ascites." (PMID 31443261, 2019). "Carboplatin significantly increased expression of HAS2, HAS3 and ABCC2 and HA secretion in ovarian cancer cell conditioned media." (PMID 24124770, 2013). "For patients in grade I + II high expression of HAS2 showed a negative impact on the OS of ovarian cancer patients (HR = 1.44, p-value = 0.013)." (PMID 35767191, 2022). "Our TNMplot analysis of over 700 ovarian cancer specimens revealed that HAS1, HYAL1 and HYAL4 mRNA expression is significantly upregulated, whereas HAS2, HYAL2 and HYAL3 mRNA expression is significantly downregulated in ovarian cancer tissue compared to controls." (PMID 35767191, 2022). "In this respect, HAS2 does not seem to play a central role with regard to the sensitivity of ovarian cancer cells to the chemotherapies taxol and cisplatin." (PMID 35767191, 2022). "Treatment with carboplatin significantly increases expression of HAS2 and HAS3, and the resultant increase of HA secretion may contribute to chemoresistance in ovarian cancer." (PMID 29849953, 2018).